CXCR4 (C-X-C motif chemokine receptor 4)
Diseases named in the same sentence as CXCR4 in open-access papers (continued):
Sharing a sentence is not in itself a finding about the gene and the disease.
myocardial infarction (101 papers, 2008 to 2025). Gross necrosis of the myocardium, as a result of interruption of the blood supply to the area, as in coronary thrombosis. "[68Ga]Ga-Pentixafor PET imaging targets CXCR4, a receptor implicated in inflammation-related cardiovascular diseases, including progressive atherosclerosis and acute myocardial infarction." (PMID 40143163, 2025). "Nonetheless, [18F]AlF-NOTA-DV1-k-(DV3) has proven its potential as translational diagnostic radiotracer for imaging of CXCR4 up-regulation, not only in an oncological setting but potentially also in preclinical models of myocardial infarction, infection or inflammation." (PMID 34683912, 2021). "This review aims to provide insight into the current concept of the CXCL12/CXCR4 axis in myocardial infarction (MI) and its underlying pathologies such as atherosclerosis and injury-induced vascular restenosis." (PMID 24966838, 2014). "For example, exosomes enriched with CXCR4 derived from CXCR4-overexpressing rat bone marrow mesenchymal stem cells have been shown to protect cardiomyocytes against ischemic damage in both a rodent model of myocardial infarction and an in vitro model." (PMID 41244150, 2025). "Beyond cancer, a study of acute myocardial infarction in mice discovered an elevated T cell-mediated recovery rate after treatment with the CXCR4 antagonist POL5551." (PMID 40581668, 2025). "Previous studies have reported that SDF-1α and its receptor, CXCR4, or SDF-1/CXCR4 axis was cardioprotective after myocardial infarction, including attenuation of adverse ventricular remodelling and preservation of ventricular function." (PMID 38555431, 2024). "In myocardial infarction inflammation, CXCR4 upregulation activates the nuclear translocation and phosphorylation of NF-κB, thus promoting NLRP3 inflammasome activation." (PMID 39684834, 2024). "First PDGF-BB pretreatment increased the cell surface expression of CXCR4, and UTMD upregulated the expression of SDF-1 in myocardial infarct tissue, while the interaction between CXCR4 and SDF-1 improved the migration and homing abilities of implanted MSCs." (PMID 38102643, 2023). "Compared to treatment with vehicle, the sequential treatment with the β3-AR agonist mirabegron and the CXCR4 antagonist AMD3100 (MA treatment) led to significant increase in circulating MSCs at day 5 post myocardial infarction." (PMID 36263604, 2023). "As one of the first investigations undertaken, the team confirmed the presence of CXCR4+, C-kit+, and C-met+ cells circulating in the blood of patients who suffered from myocardial infarction." (PMID 36830880, 2023). "Studies have shown that the expression of CXCR4 increased significantly after acute myocardial infarction in diabetic mice." (PMID 36465455, 2022). "The chemokine SDF-1α, upregulated early after myocardial infarction, attracts the homing and engraftment of CXCR4+ sorted ASCs to target region via SDF-1α/CXCR4 interaction." (PMID 36051532, 2022). "In this regard, numerous studies have already reported on the feasibility of CXCR4-directed PET in patients after myocardial infarction." (PMID 35674738, 2022). "In progressive atherosclerosis and acute myocardial infarction, recruitment of leukocytes to the injured region by the CXCR4/CXCL12 pair is thought to be a component of the healing response." (PMID 35028820, 2022). "Studies have revealed that SDF-1/CXCR4 axis is highly important for bone marrow stem cells migration to the injury sites under various pathologies, including spinal cord lesions, myocardial infarction and cerebral ischemia." (PMID 33461165, 2021). "To evaluate systemic immune activation in response to myocardial infarction, we measured CXCR4 signal from the spleen as a hematopoietic reservoir." (PMID 34335975, 2021). "PET-guided CXCR4 inhibition by AM3100 in CXCR4-upregulated cells demonstrated improved left ventricular outcomes in murine myocardial-infarction models." (PMID 34494495, 2021).
myocardial infarction (continued). "One example is CXCR4 which can be targeted by 68Ga-pentixafor; uptake of this tracer was increased after myocardial infarction." (PMID 34485416, 2021). "Clinical trials targeting CXCR4 have been used to mobilize EPCs for tissue repair during myocardial infarct and ischemia." (PMID 31245040, 2019). "Most likely, the elevated CXCR4 expression in myocardial infarction and atherosclerotic plaques, as measured by [68Ga]Pentixafor PET, originates from infiltrating leukocytes to the infarct area and the atherosclerotic lesion, respectively." (PMID 30105558, 2018). "[68Ga]Pentixafor identifies myocardial inflammation early after acute myocardial infarction, and first both experimental and clinical studies support its use to determine vessel wall CXCR4 expression." (PMID 29967943, 2018). "Multiple studies, examining CXCR4 expression after acute myocardial infarction, showed, that the PET signal correlated with the extent of infarcted myocardium, as measured by cardiac MRI." (PMID 30105558, 2018). "Clinical PET/CT, combined with motion-correction techniques, identified upregulated CXCR4 signal in culprit coronary lesions early after myocardial infarction and stent-based reperfusion." (PMID 29967943, 2018). "For instance, the pharmacological manipulation of CXCR4 pathway finds application in contrasting the detrimental effects of ischemic disease and myocardial infarction as well as in management of rheumatoid arthritis and liver fibrosis." (PMID 29240722, 2017). "R. glutinosa extracts enhanced the migration, mobilization and therapeutic angiogenesis of endothelial progenitor cells after myocardial infarction by activating the SDF-1/CXCR4 cascade." (PMID 26264147, 2015). "This study examined the role of exosomes derived from MSC overexpressing CXCR4 for recovery of cardiac functions after myocardial infarction (MI)." (PMID 26074976, 2015). "Much is known about the SDF-1α–CXCR4/CXCR7 axis in the context of myocardial regeneration after acute myocardial infarction (‘chronic cardioprotection’)." (PMID 24704323, 2014). "CXCR-4 has been shown to protect the heart after myocardial infarction via promoting stem cell recruitment." (PMID 25192254, 2014). "Moreover, accelerated disruption of the microvascular architecture with chronic CXCR4 blockade was associated with augmented renal decline and progressive renal fibrosis, analogous to the exacerbation of cardiac dysfunction with chronic CXCR4 blockade in the post-myocardial infarction setting." (PMID 24637920, 2014). "In mice with acute myocardial infarction, the local trophic effects of infused MSCs required cardiac myocyte (CM)-CXCR4 expression and were mediated by SDF-1 secretion." (PMID 24381939, 2013). "The SDF-1/CXCR4 axis has been shown to be significantly upregulated in many experimental models of tissue injury such as myocardial infarction, ischemic brain lesion, acute kidney injury, and burn wounds." (PMID 24381939, 2013). "SDF-1α has been shown to be significantly upregulated in many experimental models including myocardial infarction and attract the CXCR4+ stem cells towards SDF-1α gradient." (PMID 22984452, 2012). "There was a significant positive correlation between CD34+CXCR4+ cells mobilization and left ventricle ejection fraction in first 24 hours after myocardial infarction (r = 0, 39, P = 0,03)." (PMID 22547906, 2012). "Recently, CXCR4 has gained attention in cardiovascular disease, especially in conditions like atherosclerosis and acute myocardial infarction, where it, along with its ligand, CXCL12, contributes to leukocyte recruitment to injured areas, driving the inflammatory response." (PMID 40143163, 2025). "What is important in the context of our study is that apelin also significantly improves cardiac function and repair after myocardial infarction by increasing angiogenesis, stromal cell-derived factor-1α, chemokine receptor 4 (CXCR-4) and homing of vascular progenitor cells." (PMID 41198895, 2025).
myocardial infarction (continued). "Imaging-guided CXCR4 inhibition accelerated inflammatory resolution and improved outcome, supporting a molecular imaging-based theranostic approach to guide therapy after myocardial infarction." (PMID 40143163, 2025). "These beneficial effects were attributed to the upregulation of the Akt signaling pathway, suggesting that CXCR4-enriched exosomes may be a viable therapeutic strategy for promoting cell survival and angiogenesis after myocardial infarction." (PMID 41244150, 2025). "Additionally, CXCR4-specific [68 Ga]Ga-pentixafor uptake increased in the infarct region of the myocardium in an experimental model of acute myocardial infarction." (PMID 35028820, 2022). "We examined whether CXCR4+ ASCs enhance their efficacy of migration and engraftment posttransplantation and improve heart function following myocardial infarction (MI)." (PMID 36051532, 2022). "Moreover, CXCR4 was considered as a therapeutic target for acute myocardial infarction due to its role in inflammation and progenitor cell recruitment." (PMID 35048778, 2022). "Furthermore, inhibition of the CXCL12/CXCR4 axis can improve cardiac fibrosis and promote tissue repair after myocardial infarction." (PMID 35668739, 2021). "In one study, uptake of the CXCR4-targeted tracer 68Ga-pentixafor peaked in the infarct region 3 days post-myocardial infarction in mice and corresponded with a flow cytometry-based peak of circulating CD45+ leukocytes and histological staining of macrophages and granulocytes within the infarct." (PMID 34196824, 2021). "Accordingly, CXCL12-secreting MSCs have improved wound healing, dermal fibroblast migration and new blood vessel formation, whereas CXCR4-overexpressing MSCs improved the outcome of myocardial infarction by increasing cell engraftment and angiogenesis and reducing myocardial remodeling." (PMID 33796536, 2021). "A phase II trial evaluated the role of POL6326 (a CXCR4 antagonist) as a stem-cell mobilizer and whether it can improve heart function after myocardial infarction (NCT01905475; EudraCT 2012- 003229-91)." (PMID 34494495, 2021). "In 2015, Kang et al44 revealed that exosomes derived from CXCR4‐overexpressing MSCs could better protect cardiomyocytes and increase angiogenesis in rat hearts after myocardial infarction." (PMID 32597574, 2020). "These properties may be suitable for PET/CT imaging of myocardial infarction, an emerging application of CXCR4 molecular imaging." (PMID 31022852, 2019). "The SDF-1α/CXCR4 axis has garnered considerable interest due to its role in stem cell homing, angiogenesis and ventricular remodelling after myocardial infarction, and has been used to target stem cells to ischaemic tissue, thereby improving LV dimensions and function." (PMID 26482377, 2015). "Furthermore, CXCR4 has been intensively studied in conditions of injury and ischemia, such as vascular restenosis upon stent implantation or myocardial infarction, respectively, as reviewed in detail recently elsewhere." (PMID 26347749, 2015). "Consequently a reduction of the CXCR4 level diminishes this important process in regeneration but inversely a decreased expression of CXCR4 was efficient to limit myocardial infarct size in mice." (PMID 22807925, 2012). "In line with the present study, initial evidence for a role of SDF-1 in cardiogenesis was postulated by the observed cardiac phenotype in knockout transgenic strains, and by the established role of the CXCR4/SDF-1 signaling axis in cardiac regeneration after myocardial infarction." (PMID 20376342, 2010). "It is suggested that CXCL12/CXCR4 interaction is important, especially in the injury-related stem cell recruitment after myocardial infarction, whereas CXCL12 action alone seems to be insufficient for mobilization of CXCR4 expressing cells in physiological situations." (PMID 18298660, 2008).
myocardial infarction (continued). "MIF promotes cardiac fibroblast proliferation through the Src kinase signaling pathway, induces proinflammatory gene expression during myocardial infarction (MI), and promotes survival via CXCR4/AKT signaling." (PMID 40092999, 2025). "Our findings indicated that CXCR4+ sorted ASCs represented a subpopulation capable of adhering to endothelial cells and migrating into infracted tissue more efficiently than did unfractionated ASCs, eventually improving cardiac function after myocardial infarction." (PMID 36051532, 2022). "DC extract can also enhance the mobilization and migration of endothelial progenitor cells after MI by activating the SDF-1α/CXCR4 cascade, showing that RGE can promote capillary regeneration in the chronic phase of myocardial infarction." (PMID 35600953, 2022). "C-X-C motif chemokine receptor 4 (CXCR4), a leukocyte G-protein-coupled receptor that is involved in several inflammatory and autoimmune disorders, has also been shown to play a role in the mediation and resolution of inflammation in patients with acute myocardial infarction (MI)." (PMID 34959686, 2021). "The SDF-1/CXCR4 axis has previously been studied in the setting of myocardial infarction (MI) and ischemia reperfusion injury." (PMID 30837882, 2019). "In addition, CXCR4 expression might reveal the myocardial healing potential, as assessed by follow-up imaging months after acute myocardial infarction." (PMID 30105558, 2018). "In addition, SDF-1α/CXCR-4 has been shown to protect the hearts after myocardial infarction." (PMID 22558265, 2012). "Stromal cell-derived factor-1α (SDF-1α) and its receptor, C-X-C chemokine receptor type 4 (CXCR4), are critical for the recruitment, homing, and engraftment of transplanted ASCs into a myocardial infarction damage site." (PMID 38132104, 2023). "Another active molecular NO microbubble combined with ultrasound technology also enhanced the therapeutic efficiency of MSCs in myocardial infarction by enhancing the SDF-1 and CXCR4 interaction." (PMID 34510332, 2022). "Determine if myocardial infarct severity and diabetes interactively influence the migratory activity of CD34+/CXCR4+ progenitor cells and if the migratory test predicts cardiac outcomes." (PMID 36465463, 2022). "Current research has indicated that CXCR4 antagonist AMD3100 facilitates angiogenesis and improves cardiac contractile function after myocardial infarction." (PMID 35173552, 2022). "CXCR4+ sorted ASCs exhibit more robust migration and engraftment into infarcted myocardium and provide better cardiac functional recovery after myocardial infarction than do unfractionated ASCs; they may serve as a promising candidate for myocardial infarction." (PMID 36051532, 2022). "Platelet CXCR4/CXCR7 surface expression is significantly elevated in coronary artery disease (CAD) patients and influences prognosis following myocardial infarction (MI)." (PMID 33114406, 2020). "It acts as the unique ligand for its receptor CXCR4 and the SDF-1–CXCR4 axis is up-regulated in both experimental and clinical studies of myocardial infarction." (PMID 24704323, 2014). "SDF was transiently upregulated in infarct and peri-infarct regions in experimental animal models of myocardial infarction and SDF-1/CXCR4 interactions played a crucial role in the recruitment of BMSCs to the infarcted myocardium." (PMID 24705272, 2014). "Another group of researchers opted to label the endogenous ligand for CXCR4, SDF-1α with 99mTc, for quantitation of CXCR4 expression in myocardial infarction." (PMID 22685650, 2012). "Second, we failed to investigate the ability of CXCR4+ sorted ASCs to achieve long-term graft survival in an animal model of myocardial infarction." (PMID 36051532, 2022). "CXCR4 blockade by POL5551 promoted the mobilization of regulatory T cells, reduced the expression of inflammatory genes, enhanced angiogenesis in the infarcted region, and improved contractile dysfunction after myocardial infarction." (PMID 35048778, 2022).
myocardial infarction (continued). "In endothelial progenitor cells (EPC), expression of the C-X-C motif chemokine receptor 4 (CXCR4) is upregulated after ADO treatment, and ADO can subsequently increase EPC migration to the heart after myocardial infarction where it stimulates angiogenesis via A2BR and CXCR4-dependent mechanisms." (PMID 34830449, 2021). "The cardioprotective role of the SDF1/CXCR4 axis was already established in myocardial infarction, however, it was never studied in DOXO-induced cardiotoxicity." (PMID 28837147, 2017). "The chemokine receptor CXCR4 and its ligand CXCL12 have been shown to be a possible imaging and therapeutic target after myocardial infarction (MI)." (PMID 32676914, 2021). "Indeed, several CXCR4 small-molecule antagonists, including AMD3100, TG-0054, POL6326 and POL5551, appear to meet these requirements and have been shown to enhance tissue repair and improve cardiac function after myocardial infarction as demonstrated in AMI animal models." (PMID 36233031, 2022). "Thus, pre-treated MSCs with insulin-like growth factor 1 (IGF-1) for 48 h markedly increased the CXCR4 expression in vitro, and a greater number of MSCs treated with IGF-1 engrafted and survived in the peri-infarcted area when the cells were transplanted in a rat model of myocardial infarction." (PMID 33796536, 2021). "By using mouse acute myocardial infarction (MI) model, we found that MNCs in peripheral blood (PB) were increased significantly at day 5 after AMI as compared to control group and the number of CXCR4 positive MNCs both in bone marrow (BM) and PB was also markedly increased after MI." (PMID 22039399, 2011).